MEG3 (maternally expressed 3)
Diseases named in the same sentence as MEG3 in open-access papers (continued):
Sharing a sentence is not in itself a finding about the gene and the disease.
hepatocellular carcinoma (continued). "Ectopic expression of MEG3 in hepatoma cells significantly inhibits proliferation and induces apoptosis." (PMID 26444285, 2015). "To assess the functional consequences of deregulated MEG3 expression, we transfected hepatoma cells with MEG3 expressing vector (pcDNA3.0-MEG3), and detected its ability to inhibit cell growth by cell-counting kit–8 assay." (PMID 26444285, 2015). "For example, miR-29 can regulate the long noncoding gene MEG3 in hepatocellular cancer through promoter hypermethylation." (PMID 25045664, 2014). "miR-29 indirectly regulates expression of tumor suppressor lncRNA, maternally expressed 3 (MEG3) by acting on its methylation in hepatocellular cancer." (PMID 23936419, 2013). "Previously studies have suggested that Meg3 is a tumor suppressor lncRNA, and Meg3 is down regulated in a number of different cancers such as breast, bladder and hepatocellular carcinoma and that its downregulation increases cell proliferation in those types of cancer." (PMID 30838022, 2019). "MEG3 was lost or reduced in the majority of hepatocellular carcinoma (HCC) tissues compared to adjacent normal tissues." (PMID 36851033, 2023). "It has long been proposed that MEG3 acts as a significant tumor suppressor gene according to its characteristic decreased expression in some cancers, including non-functional pituitary adenoma, colorectal cancer, non-small cell lung cancer, hepatocellular carcinoma, neurospongioma, and meningeoma." (PMID 36968595, 2023). "Long non-coding RNAs (lncRNAs) are regulated in cancer cells, including lncRNA MEG3, which is downregulated in Hepatocellular Carcinoma (HCC)." (PMID 36005145, 2022). "HULC, MALAT-1, TUC338, TUC339, lncRNA-HEIH, MVIH, HOTAIR, lnc-RoR, and HOTTIP have all been associated with higher expression in hepatocellular carcinoma (HCC) compared with normal liver tissue, while MEG3 is repressed in HCC." (PMID 27007663, 2016). "For example, the miR-29a epigenetically modulated expression of the lncRNA MEG3 in hepatocellular carcinoma (HCC) through promoter hypermethylation." (PMID 25200485, 2014). "Based on a literature analysis, we identified MEG3 and HOTAIRM1 as inhibitors of the Wnt/β-catenin pathway in oral squamous cell carcinoma, melanoma, and hepatocellular carcinoma, suggesting a broader tumor-suppressive role." (PMID 40350996, 2025). "miR-29a was shown to regulate methylation of MEG3 via DNA methyltransferase (DNMT) 1 and 3b, thus contributing to hepatocellular carcinoma (HCC) growth." (PMID 30386180, 2018). "The same mechanism has also been reported in hepatocellular carcinoma, and miR-26a regulates cell proliferation and migration by modulating DNMT3B/MEG3 axis." (PMID 29416703, 2018). "In hepatocellular carcinoma (HCC), the maternally expressed gene 3 (MEG3) was found to be hypermethylated and down-regulated by 210-fold in HCC compared to non-malignant hepatocytes." (PMID 23976967, 2013).
hepatocellular carcinoma (continued). "The DNA methylation status of MEG3 affects its expression in human leukocytes, and therefore, miR-29-mediated suppression of the DNA methyltransferases DNMT1 and DNMT3b elevates the expression of MEG3, as demonstrated in hepatocellular cancer." (PMID 28598385, 2017). "Moreover, MEG3 also can be identified as an independent prognostic factor for RFS and OS of hepatocellular carcinoma patients, which notably suggests a major role of MEG3 in the prediction of prognosis." (PMID 27793008, 2016). "MS VLPs delivered long non-coding RNA maternally expressed gene 3 (MEG3) specifically to epidermal growth factor receptor (EGFR)-positive hepatocellular carcinoma (HCC) cell lines, without activating EGFR downstream signaling pathways." (PMID 39337427, 2024). "We investigated the effect of the long noncoding RNA (lncRNA) maternally expressed gene 3 (MEG3) on hepatocellular carcinoma (HCC) tumorigenesis and progression by targeting miR-5195-3p and transcription factor forkhead box O1 (FOXO1) to identify a novel target for HCC treatment." (PMID 34895065, 2021).
cervical carcinoma (54 papers, 2015 to 2025). A carcinoma arising from either the exocervical squamous epithelium or the endocervical glandular epithelium. "In cervical cancer, lncRNA maternally expressed gene 3 (MEG3) was reported to be conversely associated with the tumor size and lymphatic metastasis, indicating its critical role as a tumor suppressor and a potential therapeutic candidate." (PMID 30813594, 2019). "Overexpression of MEG3 in cervical cancer cells attenuated the miR-21-5p expression level, causing inhibition of proliferation, and induction of apoptosis." (PMID 30813594, 2019). "Our previous studies have revealed the decrease in MEG3 expression in cervical cancer tissues and its close association with the prognosis of patients." (PMID 31320837, 2019). "We found that MEG3 methylation is not only a risk factor for cervical cancer, but also for HR-HPV infection and lymph node metastasis." (PMID 28057015, 2017). "MEG3 shows potential for use in diagnostic applications and therapeutic interventions in cervical cancer." (PMID 28057015, 2017). "In conclusions, MEG3 methylation in plasma can serve as a diagnostic and prognostic biomarker for cervical cancer, providing useful information for clinical management." (PMID 28740189, 2017). "Kaplan–Meier analysis of patients with cervical cancer indicated that MEG3 expression level was associated with recurrence-free and overall survival." (PMID 28057015, 2017). "ROC curve and Cox regression analyses were used to assess the diagnostic and prognostic value of MEG3 in patients with cervical cancer." (PMID 28057015, 2017). "In conclusion, owing to its significant role in cervical cancer, MEG3 could potentially act as a diagnostic, prognostic, and therapeutic target." (PMID 40242248, 2025). "MEG3 caused G0/G1 arrest in prostate cancer cells and G2/M arrest in cervical cancer cells." (PMID 36851033, 2023). "However, little is known about the diagnostic value of MEG3, especially MEG3 methylation status, as a plasma-based biomarker for cervical cancer patients." (PMID 28740189, 2017). "Furthermore, hypermethylation of MEG3 in plasma was associated with worse recurrence-free and overall survival in cervical cancer patients." (PMID 28740189, 2017). "Moreover, our previous study showed that MEG3 is associated with the progression of cervical cancer via regulation of cell proliferation and apoptosis." (PMID 28057015, 2017). "MEG3 may be a useful diagnostic tool and prognostic marker for cervical cancer, and its inactivation in cervical cancer may be due to promoter hypermethylation." (PMID 28057015, 2017). "Although MEG3 has been proved to be a tumor suppressor in cervical cancer according to our previous study, the diagnostic value of MEG3 methylation in plasma is still unknown." (PMID 28740189, 2017). "For plasma MEG3 methylation was closely linked to lymph node metastasis of cervical cancer, we speculated that it might be associated with prognosis too." (PMID 28740189, 2017). "MEG3 methylation was a risk factor for cervical cancer (OR = 17)." (PMID 28057015, 2017). "Moreover, MEG3 appears to have diagnostic and prognostic value in cervical cancer." (PMID 40242248, 2025). "Therefore, MEG3 may represent a novel indicator of prognosis in cervical cancer, helping to identify high-risk patients before treatment." (PMID 28057015, 2017). "However, the diagnostic value of plasma MEG3 methylation for cervical cancer patients is still unknown." (PMID 28740189, 2017). "MEG3 binds to P-STAT3 in cervical cancer cells, leading to its ubiquitination and subsequent degradation, resulting in apoptosis and inhibition of tumor cell proliferation." (PMID 40242248, 2025). "In cervical cancer tissues and cell lines, the expression of MEG3 and STC1 is diminished, while the expression levels of miR-7-5p are elevated." (PMID 40242248, 2025).
cervical carcinoma (continued). "Specifically, oncogenic lncRNAs, such as HOTAIR and MALAT1, are significantly upregulated in EVs from cervical cancer patients, while the tumor-suppressive lncRNA MEG3 is significantly downregulated." (PMID 40809518, 2025). "A multi-analyte detection model integrating HOTAIR, MALAT1, and MEG3 expression patterns achieves high-precision stratification of cervical cancer patients, HPV-persistent carriers, and healthy controls." (PMID 40809518, 2025). "MEG3 is a tumor suppressor that influences the growth, proliferation, and apoptosis of cervical cancer cells by modulating multiple molecular pathways and signaling cascades." (PMID 40242248, 2025). "For instance, in bladder and cervical cancers, MEG3 overexpression has been shown to improve the efficacy of chemotherapeutic agents like cisplatin by promoting apoptosis and mitigating cellular invasion and survival pathways." (PMID 40242248, 2025). "Conversely, knocking down MEG3 promoted cervical cancer cell proliferation, migration, and inhibited apoptosis, particularly in the presence of cisplatin." (PMID 40242248, 2025). "Overexpression of MEG3 or inhibition of miR-7-5p induced apoptosis in cervical carcinoma cells in response to endoplasmic reticulum stress." (PMID 40242248, 2025). "This highlights the potential function of MEG3 as a tumor suppressor that is capable of inhibiting the growth of cervical cancer." (PMID 40242248, 2025). "Whereas in cervical cancer, MEG3 was reported to promote apoptosis and inhibit cell proliferation via binding to p-STAT3, which resulted in the ubiquitination and degradation of STAT3." (PMID 40548301, 2025). "In cervical cancer cells, for instance, MEG3 is downregulated where it regulates the miR-21/PTEN axis, promoting cisplatin sensitivity." (PMID 36869839, 2023). "MEG3 is low expressed in cervical cancer and negatively correlated with FIGO stage, tumor size and lymph node metastasis." (PMID 36890809, 2023). "To investigate the effect of MEG3 on cisplatin resistance in cervical cancer cells, we established Hela-CR, which IC50 values were significantly higher and the MEG3 levels were significantly lower than Hela cells." (PMID 36344947, 2022). "In a large study, the methylation level of maternally expressed 3 (MEG3) in plasma from 168 cervical cancer patients correlated with the diagnosis of cervical cancer (area under the curve (AUC) 0.867)." (PMID 35725812, 2022). "Further studies showed that the MEG3/miR-21/PTEN axis affected cisplatin sensitivity in cervical cancer cells, and these results of recue assay were used to confirm this conclusion." (PMID 36344947, 2022). "For example, lncRNA MEG3 can inhibit the proliferation of cervical cancer cells, while its expression in clinical cervical cancer specimens is significantly down-regulated, indicating that lncRNA MEGS plays an important role as a tumor suppressor gene." (PMID 33744848, 2021). "Lidocaine enhances apoptosis and reduces proliferation of cervical cancer cells by targeting the lncRNA MEG3/miR-421/BTG1 axis." (PMID 34122108, 2021). "The maternally expressed gene 3 (MEG3) lncRNA is expressed at lower levels in cervical cancer tissues than in normal cervical epithelium." (PMID 32326624, 2020). "Ectopic MEG3 expression in cervical cancer lines inhibited proliferation, increased apoptosis and reduced tumorigenicity in xenograft models." (PMID 32326624, 2020). "Also several lncRNAs, comprising among others HOTAIR, MALAT1, GAS5, and MEG3, have shown to be associated with various pathogenic processes such as tumor progression, invasion as well as therapeutic resistance and emerged as new diagnostic and prognostic biomarkers in cervical cancer." (PMID 32154165, 2020). "MEG3 has shown to act as a cancer suppressor through its ability to down regulate the miR-21-5p levels in cervical cancer cell lines." (PMID 32154165, 2020).
cervical carcinoma (continued). "Increased levels of MEG3 in cervical cancer cell lines have shown to inhibit cell proliferation, induce cell cycle arrest and cause apoptosis." (PMID 32154165, 2020). "These pathways have been reported to contribute to the regulator roles of MEG3 in a variety of cancers such as breast, meningioma, kidney, and cervical cancers." (PMID 32277605, 2020). "Mice were divided into four groups and subcutaneously injected with cervical cancer cells from the MEG3, vector, MEG3 shRNA, or NC shRNA group." (PMID 31320837, 2019). "Here, we explored the specific regulatory mechanism of MEG3 and its downstream proteins in cervical cancer cells." (PMID 31320837, 2019). "We have previously demonstrated that MEG3 expression is low in cervical cancer tissues and is closely related to the prognosis of patients." (PMID 31320837, 2019). "We first used ELISA and RT-qPCR to detect the relative expression of P-STAT3 and MEG3 in cervical cancer tissues." (PMID 31320837, 2019). "As a result, the promotion of proliferation and inhibition of apoptosis of cervical cancer cell lines by MEG3 shRNA were significantly attenuated through the antagonizing effect of niclosamide." (PMID 31320837, 2019). "In vivo tumor formation experiments showed that MEG3 inhibited the tumor formation ability of cervical cancer cells." (PMID 31320837, 2019). "In cervical cancer, MEG3 was downregulated in the cancer tissues as compared to that in corresponding normal tissues and downregulated MEG3 was associated with recurrence and short overall survival." (PMID 31729423, 2019). "Then Pearson correlation analysis indicated that the expression of MEG3 was negatively correlated with that of P-STAT3 in cervical cancer tissues (P < 0.01, R = − 0.807)." (PMID 31320837, 2019). "That means MEG3, as an upstream regulator of c-Myc, also has broad prospects in the biological treatment of cervical cancer." (PMID 31320837, 2019). "MEG3 binds to P-STAT3 in cervical cancer cells, resulting in P-STAT3 ubiquitination and degradation and apoptosis and inhibition of proliferation of tumor cells." (PMID 31320837, 2019). "The close correlation between MEG3 expression and cervical cancer was confirmed at tissue and cellular levels." (PMID 31320837, 2019). "The level of MEG3 methylation is significantly higher in cervical cancer tissues and patients' plasmas than in adjacent normal tissues and plasmas of healthy participants, respectively." (PMID 29850477, 2018). "LncRNA MEG3 as a tumor suppressor is down-regulated in cervical cancer, and MEG3 affects cell proliferation and apoptosis by regulating miR-21." (PMID 30355656, 2018). "In conclusion, the present studies clearly showed that MEG3, MYOD1, CALCA, hTERT, and RASSF1A methylation in plasma can serve as diagnostic and prognostic biomarkers for cervical cancer patients, providing useful information for clinical management." (PMID 29850477, 2018). "The statistical analysis showed that plasmas of cervical cancer patients expressed a significantly higher level of MEG3 methylation than that of healthy participants." (PMID 28740189, 2017). "Our previous study reported that MEG3 is an important tumor suppressor gene that is inactivated in cervical cancer." (PMID 28057015, 2017). "The methylation status of the MEG3 promoter in cervical cancer tissue samples was tested using methylation-specific PCR." (PMID 28057015, 2017). "The results showed that the level of MEG3 methylation was significantly higher in cervical cancer tissues and patients’ plasmas than those in adjacent normal tissues and plasmas of healthy participants respectively." (PMID 28740189, 2017). "Although extensive effort has been devoted to understanding the prognostic value of MEG3 in human tumors, little was known about its value in cervical cancer until now." (PMID 28057015, 2017).